CASC3 (CASC3 exon junction complex subunit)
Description:
Required for pre-mRNA splicing as component of the spliceosome. Core component of the splicing-dependent multiprotein exon junction complex (EJC) deposited at splice junctions on mRNAs. The EJC is a dynamic structure consisting of core proteins and several peripheral nuclear and cytoplasmic associated factors that join the complex only transiently either during EJC assembly or during subsequent mRNA metabolism. The EJC marks the position of the exon-exon junction in the mature mRNA for the gene expression machinery and the core components remain bound to spliced mRNAs throughout all stages of mRNA metabolism thereby influencing downstream processes including nuclear mRNA export, subcellular mRNA localization, translation efficiency and nonsense-mediated mRNA decay (NMD). Stimulates the ATPase and RNA-helicase activities of EIF4A3. Plays a role in the stress response by participating in cytoplasmic stress granules assembly and by favoring cell recovery following stress. Component of the dendritic ribonucleoprotein particles (RNPs) in hippocampal neurons. May play a role in mRNA transport. Binds spliced mRNA in sequence-independent manner, 20-24 nucleotides upstream of mRNA exon-exon junctions. Binds poly(G) and poly(U) RNA homomer.
Synonyms: Btz; MLN51
Tractability: Small molecule: a structure with a bound ligand is known. PROTAC: UniProt records ubiquitination sites on it; ubiquitination databases record sites on it; its protein half-life has been measured.
Gene: Protein-coding gene on chromosome 17 (40,140,278 to 40,177,001, forward strand). Ensembl gene ENSG00000108349.
Subcellular location: Cytoplasm; Cytoplasm, perinuclear region; Nucleus; Nucleus speckle; Cytoplasm, Stress granule; Cytoplasm, Cytoplasmic ribonucleoprotein granule; Cell projection, dendrite
Subcellular location (Human Protein Atlas): Nuclear membrane
Pathways (Reactome):
Metabolism of RNA: Nonsense Mediated Decay (NMD) enhanced by the Exon Junction Complex (EJC); Transport of Mature mRNA derived from an Intron-Containing Transcript; mRNA 3'-end processing; mRNA Splicing - Major Pathway
Developmental Biology: Regulation of expression of SLITs and ROBOs
Gene Ontology:
Molecular function: DEAD/H-box RNA helicase binding; enzyme binding; identical protein binding; protein binding; RNA binding; ubiquitin protein ligase binding; mRNA binding
Biological process: mRNA splicing, via spliceosome; regulation of nuclear-transcribed mRNA catabolic process, nonsense-mediated decay; regulation of RNA helicase activity; mRNA export from nucleus; mRNA processing
Cellular component: cytoplasm; exon-exon junction complex; nuclear membrane; nuclear speck; nucleoplasm; nucleus; post-spliceosomal complex; spliceosomal complex; U2-type catalytic step 1 spliceosome; U2-type catalytic step 2 spliceosome; cytosol; cytoplasmic ribonucleoprotein granule; cytoplasmic stress granule; dendrite; perinuclear region of cytoplasm; ribonucleoprotein complex
Genetic constraint (gnomAD): Loss-of-function variants: 26 observed, 77.35 expected, observed/expected ratio (o/e) 0.34, 90% interval 0.25 to 0.47. The upper end of that interval is the gene's LOEUF score, 0.47, which puts it in group 2 of 6, group 1 being the genes least tolerant of losing a copy. Missense variants: 816 observed, 951.11 expected, observed/expected ratio (o/e) 0.86, 90% interval 0.81 to 0.91. Synonymous variants: 310 observed, 344.16 expected, observed/expected ratio (o/e) 0.9, 90% interval 0.82 to 0.99.
Homologues: Orthologues: macaque CASC3 (97% identical), dog CASC3 (95% identical), rabbit CASC3 (93% identical), pig CASC3 (92% identical), mouse Casc3 (90% identical), rat Casc3 (90% identical), guinea pig CASC3 (89% identical), chimpanzee CASC3 (68% identical), tropical clawed frog casc3 (58% identical), zebrafish casc3 (51% identical), Drosophila melanogaster btz (25% identical), Caenorhabditis elegans casc-3 (19% identical).
Diseases named in the same sentence as CASC3 in open-access papers:
CASC3 is named in the same sentence as 14 diseases in open-access papers, as found by Europe PMC text mining. Sharing a sentence is not in itself a finding about the gene and the disease. The quoted sentences say what the papers report.
breast carcinoma (6 papers, 2006 to 2025). "CASC3, also known as MLN51, was first identified in breast cancer cells, and it was reported to be associated with several diseases including malignant tumors." (PMID 27029030, 2016). "In breast cancer, CASC3 expression was positively associated with patient survival." (PMID 40978141, 2025). "Genomic analysis revealed that CASC3 is highly expressed in breast cancer with HER2/TOP2A co-amplification compared with HER2-amplified breast cancer." (PMID 40978141, 2025). "Inhibition of CASC3 suppressed the expression of circ-NOL10 in breast cancer." (PMID 40978141, 2025). "This study suggested that CASC3 can regulate the expression of circ-NOL10 and govern the tumorigenesis and progression of breast cancer." (PMID 40978141, 2025).
hepatocellular carcinoma (3 papers, 2016 to 2025). A malignant tumor that arises from hepatocytes. "CASC3 overexpression significantly promoted hepatocellular carcinoma cell proliferation." (PMID 33685397, 2021).
osteoarthritis (2 papers, 2019 to 2023). A noninflammatory degenerative joint disease occurring chiefly in older persons, characterized by degeneration of the articular cartilage, hypertrophy of bone at the margins and changes in the synovial membrane. "The importin 8 (IPO8), cancer susceptibility candidate 3 (CASC3), and TBP were recommended as RGs for studies on osteoarthritis patient-derived BM-MSCs." (PMID 31240211, 2019).
asthma (1 paper, 2024). "Among the protein-coding genes causally associated with unspecified asthma in lung and blood, seven are within the 17q12-21 locus (i.e., PGAP3, IKZF3, GSDMB, ORMDL3, GSDMA, MED24, and CASC3)." (PMID 39628479, 2024).
endometriosis (1 paper, 2021). The growth of functional endometrial tissue in anatomic sites outside the uterine body. "Interestingly, we found the five most stable genes (EIF2B1, POP4, UBC, CASC3, and MRPL19) were not previously measured in endometriosis expression studies." (PMID 33686153, 2021).
gastric cancer (1 paper, 2025). A primary or metastatic malignant neoplasm involving the stomach. "In gastric cancer patients, CASC3 depletion was associated with worse prognosis." (PMID 40978141, 2025).
leukemia (1 paper, 2025). A malignant (clonal) hematologic disorder, involving hematopoietic stem cells and characterized by the presence of primitive or atypical myeloid or lymphoid cells in the bone marrow and the blood. "It is essential to determine whether an association between Smurf2 and CASC3 exists in leukemia patient samples." (PMID 40978141, 2025). "This study aims to elucidate the function and underlying mechanisms of CASC3 in leukemia." (PMID 40978141, 2025). "In the current study, we report that Smurf2 enhances CASC3 ubiquitination and degradation, thereby attenuating leukemia progression." (PMID 40978141, 2025). "The data showed that knockdown of Smurf2 prolonged the half-life of CASC3 in both leukemia cell lines." (PMID 40978141, 2025). "Strikingly, the 137–283 domain of CASC3 plays a critical role in Smurf2-mediated ubiquitination and degradation of CASC3 in leukemia." (PMID 40978141, 2025). "In the current study, we demonstrated that Smurf2 inhibits cell viability and triggers cell apoptosis in leukemia cells, identifying CASC3 as a potential substrate of Smurf2." (PMID 40978141, 2025). "To further dissect whether CASC3 is a downstream target of Smurf2, we assessed the expression of CASC3 in leukemia cells after Smurf2 modification." (PMID 40978141, 2025). "In conclusion, targeting the Smurf2/CASC3 axis may offer a potential therapeutic strategy for the treatment of leukemia." (PMID 40978141, 2025). "Altogether, these findings suggest that the 137–283 domain and K254 could be critical for Smurf2-mediated ubiquitination and degradation of CASC3 in leukemia." (PMID 40978141, 2025). "However, the role of CASC3 (MLN51) in leukemia development and progression remains poorly understood." (PMID 40978141, 2025). "In conclusion, the Smurf2/CASC3 axis may act as a potential therapeutic target for leukemia therapy." (PMID 40978141, 2025). "Additionally, shSmurf2-mediated increase in CASC3 expression was negated by shCASC3 infection in both leukemia cell lines." (PMID 40978141, 2025). "Collectively, our results suggest that the Smurf2/CASC3 axis may serve as a potential therapeutic target for the treatment of leukemia." (PMID 40978141, 2025). "To explore whether the depletion of Smurf2 enhances cell viability through governing CASC3 expression in leukemia, we infected HL-60 and K562 cells with shSmurf2 and shRNA CASC3 (shCASC3)." (PMID 40978141, 2025). "In our work, we identified that CASC3 is a substrate of Smurf2 in leukemia cells." (PMID 40978141, 2025). "Thus, Smurf2 knockdown promotes cell viability in part via regulating the expression of CASC3 in leukemia cells." (PMID 40978141, 2025). "Furthermore, the regulatory mechanisms controlling Smurf2 expression and its subsequent effect on CASC3 protein levels in leukemia remain unclear." (PMID 40978141, 2025). "Moreover, Smurf2 exerts its biological effects by regulation of CASC3 in leukemia." (PMID 40978141, 2025). "Moreover, we identified CASC3 as a substrate of Smurf2 in leukemia." (PMID 40978141, 2025). "This study does not address the downstream signaling pathways through which CASC3 promotes leukemia cell viability." (PMID 40978141, 2025).
melanoma (1 paper, 2020). A malignant, usually aggressive tumor composed of atypical, neoplastic melanocytes. "In melanoma cell lines, a geometric mean of the reference genes CASC3 and RPS2 is estimated to be the most optimal NF according to geNorm." (PMID 31567589, 2020). "For studies of gene expression in melanoma cell lines; we identified CASC3 and RPS2 as robust reference genes over 13 different melanoma cells lines." (PMID 31567589, 2020). "Thus, based on the results from the two algorithms the most optimal NF for melanoma cell lines can be calculated as a geometric mean of reference genes CASC3 and RPS2." (PMID 31567589, 2020). "We recommend using a geometric mean of the expression of CLTA, MRPL19 and ACTB for normalization of gene expression in melanomas and a geometric mean of the expression of CASC3 and RPS2 for normalization of gene expression in melanoma cell lines." (PMID 31567589, 2020). "We recommend the use of a combined geometric mean of the expression levels of CASC3 and RPS2 for normalization of gene expression in melanoma cell lines." (PMID 31567589, 2020). "CASC3 and RPS2 also were evaluated as reference genes in yet two other melanoma cell lines and a number of other cell lines of origin different from melanoma (breast and placenta), and they were found to be robustly expressed in all cases." (PMID 31567589, 2020).
meningioma (1 paper, 2011). A generally slow growing tumor attached to the dura mater. "TOST procedure showed statistical equivalence between normal tissue and meningiomas (± δ = ± 1.5) for three reference genes: CASC3 (+0.87), IPO8 (+0.57) and POP4 (+1.36)." (PMID 21806841, 2011). "Bestkeeper-1 considered CASC3 as the most stable genes in meningiomas, but ranked CASC3 only in ninth place for normal control tissue." (PMID 21806841, 2011). "Eight highest ranked reference genes (CASC3, EIF2B1, IPO8, MRPL19, PGK1, POP4, PPIA, and RPL37A) plus GAPDH and ACTB were then analyzed in 35 meningiomas, arachnoidea, dura mater and normal brain." (PMID 21806841, 2011). "Considering the results of the normalization of VEGFA against every single reference genes with significantly altered results for CASC3 and IPO8, NormFinder displays a more accurate ranking for meningiomas and their control tissue." (PMID 21806841, 2011). "Most reference genes maintained the ratio between brain, dura and meningioma except IPO8 and CASC3." (PMID 21806841, 2011). "Those three genes were not normally distributed in meningiomas (CASC3 (P-value = 0.002), IPO8 (P-value < 0.0001) and POP4 (P-value = 0.0005)." (PMID 21806841, 2011).
cancer (9 papers, 2013 to 2025). A tumor composed of atypical neoplastic, often pleomorphic cells that invade other tissues. "Circ-0091579 combatively bind with miR-490-5p, whereas miR-490-5p directly binds with Cancer susceptibility candidate 3 (CASC3)." (PMID 36672755, 2022). "It has been indicated that the newly identified RNF146 substrates basic leucine zipper nuclear factor 1 (BLZF1) and cancer susceptibility candidate 3 (CASC3) are involved in tumor development and cell proliferation." (PMID 24454854, 2014). "The splicing cluster involved genes with activity in the RNA transport pathway, specifically CASC3 (cancer susceptibility candidate 3), a component of the exon junction complex (EJC) involved in subsequent steps of splicing, such as export from the nucleus to the cytoplasm and translation." (PMID 39202342, 2024). "This included genes in which upregulation is implicated in cancer (CTDSP2, CASC3, PGF) and those that are thought to be involved in tumor suppression (SASH1, HIPK2)." (PMID 23406646, 2013). "CASC3 (also known as metastatic lymph node 51 (MLN51)) is involved in different types of cancer." (PMID 36672755, 2022). "For buffy coat samples [n = 58; 30 controls, 28 cancers (stages II: 13, III: 6, IV: 9)], CASC3 had the lowest standard deviation." (PMID 39146279, 2024). "The second analysis used CASC3 as the normalizing gene, and only identified two TaqMan assays (RPL8, TMBS10) that were classified as statistically significant, and they were both downregulated in cancer patients." (PMID 39146279, 2024).
tumor (7 papers, 2011 to 2025). "Collectively, these results suggest that Smurf2 suppresses tumor growth in vivo, potentially by downregulating CASC3." (PMID 40978141, 2025). "Immunohistochemistry staining of tumor sections also supported the finding that CASC3 expression was downregulated in tumors with Smurf2 overexpression." (PMID 40978141, 2025). "Western blotting analysis of tumor tissues showed that overexpression of Smurf2 reduced CASC3 expression." (PMID 40978141, 2025). "Strikingly, the downregulation of Smurf2 promotes cell viability through CASC3, while overexpression of Smurf2 retards tumor growth in mouse models." (PMID 40978141, 2025). "MiR-124-1 restoration not only significantly decreased the expression of CASC3, but also attenuated the tumor-promoting activity of HCC cells in vitro." (PMID 27029030, 2016). "Normalization with IPO8 or CASC3 showed significantly increased ratio for brain to dura and brain to tumour." (PMID 21806841, 2011). "Tumour tissue and normal tissue group of five candidate reference genes (CASC3, CDKN1B, POLR2A, PUM1 and UBC) were statistically equivalent to within ± 1.5." (PMID 21806841, 2011). "Moreover, further studies should assess whether Smurf2 overexpression inhibits tumor growth through regulation of CASC3 in vivo." (PMID 40978141, 2025). "The tumor volumes of the MHCC-LM3-miR-124-1 and MHCC-LM3-Sh-CASC3 induced tumors were significantly reduced." (PMID 27029030, 2016). "In the current study, we observed that CASC3 overexpression promoted HCC cell proliferation and colony formation, and these effects were confirmed in vivo in a xenograft tumor model." (PMID 27029030, 2016). "We further investigated contexts of these spMOCA’s hub genes, where we identified specific prognostic genes serves as hub genes in the same tumor type, for example, WIPF2 and CASC3 for BRCA, COX6A1 and PRAP1 for CRC, E2F1 and AKR1C3 for LUSC, and TSPAN3 and SLC4A11 for OVCA." (PMID 41370198, 2025).
infection (2 papers, 2020 to 2025). The state of being infected such as from the introduction of a foreign agent such as serum, vaccine, antigenic substance or organism. "A cycloheximide chase assay was performed to measure half-life of CASC3 in HL-60 and K562 cells after shSmurf2 infection." (PMID 40978141, 2025). "As expected, shCASC3 infection reduced the expression of CASC3 in both HL-60 and K562 cell lines." (PMID 40978141, 2025). "NMD inhibition (+U1D) and PEMV2 infection resulted in increased transcript levels for SMG7, SMG9, UPF1, UPF3, and CASC3, whereas HA-p26 expression increased transcript levels only for SMG7, SMG9, and UPF3." (PMID 32156817, 2020). "In both HL-60 and K562 cells, shSmurf2 infection decreased the expression of Smurf2 but did not alter CASC3 mRNA levels." (PMID 40978141, 2025).
CASC3 also shares sentences with these, for which no sentence is quoted: liver cancer (1 paper); rheumatoid arthritis (1).